ALKBH5 (alkB homolog 5, RNA demethylase)
Diseases named in the same sentence as ALKBH5 in open-access papers (continued):
Sharing a sentence is not in itself a finding about the gene and the disease.
ovarian carcinoma (continued). "ALKBH5 (AlkB Homolog 5, RNA Demethylase) expression is increased in ovarian cancer tissues and cells (A2780, SKOV3 cell lines), where it contributes to cancer cell proliferation, migration, and autophagy." (PMID 35884580, 2022). "In human ovarian cancer, ALKBH5 and TLR4 amounts are elevated in cancer cells after co-culture with alternatively activated (M2) macrophages." (PMID 35063010, 2022). "Ovarian cancer cells co-cultured with macrophages showed higher expression of m6A demethylase ALKBH5 and TLR4." (PMID 33814008, 2021). "Their study confirmed that ALKBH5 regulates autophagy initiation in ovarian cancer and that ALKBH5 knockout activates autophagy." (PMID 34794452, 2021). "Additional evidence showed that ALKBH5 was highly expressed in ovarian cancer tissue, but decreased in cancerous cell lines, whose expression pattern is consistent with Toll-like receptor (TLR4)." (PMID 33611339, 2021). "Silencing of ALKBH5, an m6A eraser, suppresses proliferation and invasion of ovarian cancer cells by enhancing autophagy." (PMID 33795529, 2021). "The results showed that the expression level of ALKBH5 mRNA in normal ovarian cell line was significantly higher than those in ovarian cancer cell lines (P < .05)." (PMID 32329191, 2020). "In this experiment, expression level of ALKBH5 in ovarian cancer tissue and normal ovarian tissues was first examined." (PMID 32329191, 2020). "In the ovarian cancer cells co‐cultured with M2 macrophages, the expression of ALKBH5 and TLR4 increased." (PMID 32329191, 2020). "M1 and M2 macrophages were co‐cultured with ovarian cancer cells to simulate a tumour microenvironment, respectively, in which the expression levels of ALKBH5 during transcription and translation were increased." (PMID 32329191, 2020). "Showing higher ALKBH5 expression, two ovarian cancer cell lines A2780 and HO8910 were selected for the following functional experiments." (PMID 32329191, 2020). "To illustrate this interaction, we used a simulated TME to verify the expression of ALKBH5 in ovarian cancer tissue and the related regulatory mechanism." (PMID 32329191, 2020). "In the present study, we demonstrated that the expression of ALKBH5 was elevated in ovarian cancer tissue but lowered in ovarian cancer cell lines." (PMID 32329191, 2020). "Marked expression of ALKBH5 has been detected in ovarian cancer, which mediates the EGFR-PIK3CA-AKT-mTOR-signaling pathway, a key regulatory pathway in autophagy-induced stress response and nutrient deprivation." (PMID 33511112, 2020). "In the present study, ALKBH5 showed higher expression in ovarian cancer tissue than in normal ovarian tissue, but lower expression in ovarian cancer cell lines than in normal ovarian cell lines." (PMID 32329191, 2020). "The results showed that the expression level of ALKBH5 in ovarian cancer tissue was significantly higher than that in normal ovarian tissue (P < .05)." (PMID 32329191, 2020). "Silencing ALKBH5 can enhance autophagy and inhibit the proliferation and invasion of ovarian cancer cells." (PMID 31808521, 2019). "ALKBH5 expression was significantly higher in the epithelial ovarian cancer samples than in the normal ovary tissues (P < 0.05)." (PMID 30987661, 2019). "The role of ALKBH5 in tumor formation of ovarian cancer cells, SKOV3 and A2780, was determined using an animal model." (PMID 30987661, 2019). "The silencing of ALKBH5 resulted in significantly decreased protein levels of HuR in ovarian cancer SKOV3 cells." (PMID 30987661, 2019). "Herein, we found that ALKBH5 inhibited autophagy and promoted proliferation and invasion of ovarian cancer." (PMID 30987661, 2019). "In the present study, we investigated the expression and function of ALKBH5 in epithelial ovarian cancer with respect to its potential role in the tumorigenesis of the disease as well as an early diagnostic marker." (PMID 30987661, 2019).
ovarian carcinoma (continued). "Overall, the present study identified ALKBH5 as a candidate oncogene in epithelial ovarian cancer and a potential target for ovarian cancer therapy." (PMID 30987661, 2019). "The expression of ALKBH5 was found to be increased in epithelial ovarian cancer tissue as compared to the normal ovarian tissues." (PMID 30987661, 2019). "Conversely, levels of the m6A demethylase “erasers,” including FTO and ALKBH5, were increased in kidney cancer and leukemia but decreased in BC, brain, CNS and ovarian cancer." (PMID 30953473, 2019). "The present study examined the expression of ALKBH5 in normal ovary tissues and ovarian cancer tissue using IHC." (PMID 30987661, 2019). "In the present study, we observed an increased expression of ALKBH5 in epithelial ovarian cancer tissues." (PMID 30987661, 2019). "This study confirms that ALKBH5 is a tumor-promoting gene in epithelial ovarian cancer, which is involved in the mTOR pathway and BCL-2-Beclin1 complex." (PMID 30987661, 2019). "Silencing ALKBH5 inhibited the proliferation, migration and enhanced the autophagy in ovarian cancer SKOV3 cells." (PMID 30987661, 2019). "In the present study, we elucidated the expression of ALKBH5 and its potential clinical significance in epithelial ovarian cancer, in order to clarify the putative function of ALKBH5 in malignancy, progression, and prognosis of cancer." (PMID 30987661, 2019). "Due to the expression value of ALKBH5, ovarian cancer patients were divided into two groups." (PMID 38637813, 2024). "ALKBH5 plays an important role in the progression of ovarian cancer." (PMID 38098223, 2024). "The DEGs were collected to investigate the biological role of ALKBH5 played in ovarian cancer." (PMID 38637813, 2024). "However, we found that the expression level of IGF2BP2 was much lower than ALKBH5 in ovarian cancer immune microenvironment." (PMID 38637813, 2024). "The function of ALKBH5 played in ovarian cancer was further analyzed through GO and KEGG analysis." (PMID 38637813, 2024). "The results showed that high expression of ALKBH5 and IGF2BP2 was associated with a poorer prognosis both in OS and PFS analysis in ovarian cancer, which might be due to its high expression in M2 macrophages in ovarian cancer microenvironment." (PMID 38637813, 2024). "Furthermore, we analyzed the prognostic value of ovarian cancer based on the expression level of ALKBH5 and IGF2BP2 with distinct phenotypes of macrophage expressions." (PMID 38637813, 2024). "Studies have shown that ALKBH5 is overexpressed and m6A modification levels are reduced in ovarian cancer with lymph node metastasis and that the ALKBH5/m6A-ITGB1/FAK signalling axis plays an important role in ovarian cancer lymphangiogenesis and lymph node metastasis." (PMID 36894952, 2023). "ALKBH5 could likewise increase the expression of NANOG mRNA by mediating its demethylation in ovarian cancer cells and enhancing its invasiveness through the NF-κB pathway." (PMID 37007161, 2023). "ALKBH5 mRNA was increased in epithelial ovarian cancer tissue as compared to the normal ovarian tissues and ALKBH5 silencing could inhibit the proliferation and invasion of epithelial ovarian cancer cells." (PMID 35444654, 2022). "Moreover, the high expression of ALKBH5 was found in cisplatin-resistant epithelial ovarian cancer cells to promote cell proliferation and chemoresistance to cisplatin in vivo and in vitro." (PMID 35628623, 2022). "ALKBH5 significantly promoted the occurrence of ovarian cancer in vivo." (PMID 34794452, 2021). "In addition, ALKBH5 is also involved in the biological regulation of many cancers, such as ovarian cancer,colon cancer, pancreatic cancer, and gastric cancer." (PMID 34794452, 2021).
ovarian carcinoma (continued). "ALKBH5 was also found upregulated in ovarian cancer tissues compared to normal ovarian tissues." (PMID 33814008, 2021). "However, when ovarian cancer cells were co-cultured with M2 macrophages, the expressions of ALKBH5 and TLR4 were both increased." (PMID 33611339, 2021). "ALKBH5 is elevated in epithelial ovarian cancer, silencing of ALKBH5 enhances the autophagy signaling and inhibits the proliferation and invasion abilities of ovarian cancer cells by reducing EGFR/PI3K/AKT signaling activity through physically interacting with HuR204." (PMID 33611339, 2021). "Collectively, ALKBH5 could promote the proliferation and inhibit the apoptosis of ovarian cancer cells." (PMID 32329191, 2020). "Furthermore, Western blot found that the protein expression level of ALKBH5 was also increased in ovarian cancer tissue, but decreased in normal ovarian cells (P < .05)." (PMID 32329191, 2020). "ALKBH5 expression was found to be significantly up‐regulated in ovarian cancer tissue." (PMID 32329191, 2020). "In conclusion, NANOG was a downstream target of ALKBH5 that might promote ovarian cancer development through demethanizing NANOG." (PMID 32329191, 2020). "Taken together, ALKBH5 plays a pivotal role in ovarian cancer growth and metastasis." (PMID 32329191, 2020). "ALKBH5 was found to play an oncogenic role in epithelial ovarian cancer." (PMID 33240891, 2020). "Silencing ALKBH5 enhanced autophagy in ovarian cancer SKOV3 cells." (PMID 33552994, 2020). "However, in vitro level of ALKBH5 was lower in ovarian cancer cell lines than that in normal ovarian cell lines." (PMID 32329191, 2020). "We first tested the expression of ALKBH5 in ovarian cancer tissue and cell lines." (PMID 32329191, 2020). "The potential role of ALKBH5 in the development of ovarian cancer, however, is rarely reported." (PMID 32329191, 2020). "Ovarian cancer patients with high expression of ALKBH5 had a poor OS and PFS." (PMID 30987661, 2019). "In addition, the upregulation of ALKBH5 expression promoted the proliferation, invasion, and autophagy in epithelial ovarian cancer cells." (PMID 30987661, 2019). "Thus, we speculated that ALKBH5 might participate in regulating the immune response in ovarian cancer microenvironment." (PMID 38637813, 2024). "Therefore, ALKBH5 is a promising target for ovarian cancer molecular therapy." (PMID 38098223, 2024). "This prompted us to confirm whether ALKBH5 regulates FOXM1 via PVT1 RNA in ovarian cancer." (PMID 38098223, 2024). "Thus, we paid more attention to investigating the role that ALKBH5 played in ovarian cancer." (PMID 38637813, 2024). "Thus, we explored the correlation between ALKBH5 and immune inhibitors, which also showed ALKBH5 might influence the immune response in the ovarian cancer immune microenvironment." (PMID 38637813, 2024). "ALKBH5 may promote the development of ovarian cancer by demethylating NANOG." (PMID 34794452, 2021). "In addition, the ectopic expression of ALKBH5 inhibited the autophagy of epithelial ovarian cancer cells in vitro and in vivo, partly through activating EGFR-PIK3CA-AKT-mTOR signaling pathway, promoting the stability of BCL-2 mRNA, as well as enhancing the interaction between Bcl-2 and Beclin1." (PMID 32742194, 2020). "However, how ALKBH5 expression drives ovarian cancer development remains unanswered." (PMID 32329191, 2020). "So, we determined whether ALKBH5 regulated the autophagy in ovarian cancer." (PMID 30987661, 2019). "ALKBH5 raised NANOG expression through the demethylation of NANOG mRNA, which accelerated ovarian cancer development." (PMID 40001461, 2025). "In ovarian cancer cells co-cultured with M2-type macrophages, activation of the TLR4 signaling pathway upregulates ALKBH5." (PMID 41562066, 2025). "In ovarian cancer, m6A regulators such as METTL3 and ALKBH5 modulate immune checkpoint expression, including PD-L1, impacting T-cell function and infiltration." (PMID 41029427, 2025).
ovarian carcinoma (continued). "In ovarian cancer, NGR-modified biomimetic nanovesicles (NGR-BNVs) achieved efficient delivery of ALKBH5 siRNA, markedly suppressing tumor proliferation and inducing apoptosis." (PMID 41562066, 2025). "We first found that ALKBH5 and IGF2BP2 were up-regulated in M2 macrophages, and both showed significantly correlated with immune cells in ovarian cancer, especially macrophages." (PMID 38637813, 2024). "In cBioPortal database, we analyzed the copy number alterations of ALKBH5 and IGF2BP2 in ovarian cancer." (PMID 38637813, 2024). "Based on these analysis, we found that ALKBH5 and IGF2BP2 could regulate the immune status of ovarian cancer microenvironment mainly through its mRNA expression levels, the mutation status of ALKBH5 and IGF2BP2 might not influence the immune status of ovarian cancer." (PMID 38637813, 2024). "For single-cell analysis, sc-TIME and HPA softwares were used to analyze the roles of ALKBH5 and IGF2BP2 played in immune cells in ovarian cancer." (PMID 38637813, 2024). "Here, we aimed to explore the role of m6A methylation enzymes ALKBH5 and IGF2BP2 in regulating macrophage polarization in ovarian cancer microenvironment." (PMID 38637813, 2024). "In this study, we found that among all the immune cells, ALKBH5 and IGF2BP2 showed the closest correlation with macrophages in ovarian cancer." (PMID 38637813, 2024). "According to our analysis, we found that ALKBH5 and IGF2BP2 were significantly correlated with the immune response in ovarian cancer." (PMID 38637813, 2024). "In conclusion, our study demonstrated that ALKBH5 and IGF2BP2 were significantly up-regulated in M2 macrophages, which not only showed closely correlation with macrophage expression in ovarian cancer, but also correlated with the prognosis of ovarian cancer." (PMID 38637813, 2024). "Upregulated ALKBH5 demethylated the long noncoding RNA PVT1 and thus stabilized FOXM1, at least partially, in ovarian cancer." (PMID 38098223, 2024). "Next, we would like to investigate the correlation of ALKBH5 and IGF2BP2 with immune cells expression in ovarian cancer microenvironment." (PMID 38637813, 2024). "TIMER2.0 and GSCA database were used to explore the immune analysis of ALKBH5 and IGF2BP2 in ovarian cancer." (PMID 38637813, 2024). "Our research for the first time demonstrated that ALKBH5 promotes EMT and facilitates intraperitoneal metastasis in ovarian cancer cells." (PMID 38505602, 2024). "In this study, we observed that FSH induced the upregulation of the m6A demethylase ALKBH5 and led to the promotion of EMT in ovarian cancer cells." (PMID 38505602, 2024). "Further validated the roles of ALKBH5 and IGF2BP2 played in ovarian cancer, GSCA software were used." (PMID 38637813, 2024). "In this study, we investigated the roles of m6A demethylase ALKBH5 and m6A recognition protein IGF2BP2 played in regulating macrophages polarization in ovarian cancer." (PMID 38637813, 2024). "To deepen our understanding the role of ALKBH5 and IGF2BP2 play in ovarian cancer immune microenvironment, we used various databases to explore their relationships with immune cells, not only at tissues level, but also at single-cell level." (PMID 38637813, 2024). "Thus, targeting ALKBH5 in macrophages might be a promising target for regulating the immune microenvironment in ovarian cancer, which could further influence the prognosis of ovarian cancer patients." (PMID 38637813, 2024). "ALKBH5 triggers Snail mRNA m6A demethylation on its CDS region to increase Snail protein expression, thus induces EMT and ovarian cancer metastasis." (PMID 38505602, 2024). "Taken together, our finding indicated that FSH increases ALKBH5 to enhance EMT and metastasis of ovarian cancer." (PMID 38505602, 2024). "To investigate the prognostic role of ALKBH5 and IGF2BP2 played in ovarian cancer, we used the online K-M plotter database." (PMID 38637813, 2024).
ovarian carcinoma (continued). "To explore the role of ALKBH5 and IGF2BP2 in immune cells at single-cell level in ovarian cancer, we found that ALKBH5 was widely expressed in immune cells, but its expression was highly expressed in macrophages." (PMID 38637813, 2024). "In conclusion, we demonstrate that ALKBH5 promotes tumour progression by at least partially stabilizing PVT1 and FOXM1 in ovarian cancer." (PMID 38098223, 2024). "K-M plotter and TIMER2.0 databases were used to evaluate the prognostic role of ALKBH5 and IGF2BP2 in ovarian cancer." (PMID 38637813, 2024). "In this study, we found that ALKBH5 and IGF2BP2 were up-regulated in M2 macrophages, which showed closely correlation with immune cells expressions in ovarian cancer, especially with macrophages." (PMID 38637813, 2024). "In various ovarian cancer studies, the erasers FTO and ALKBH5 regulate various biological processes." (PMID 37194218, 2023). "Patients with ovarian cancer had low levels of FTO and ALKBH5, whereas those with higher levels of both presented shorter overall survival and progression-free survival (PFS)." (PMID 37194218, 2023). "CDH2, ALKBH5, ELAVL1, and WTAP are the key regulators that exert a critical impact on the development and prognosis of ovarian cancer." (PMID 37684273, 2023). "Simultaneously, to understand the biology behind the key signatures, the protein expression of ALKBH5, WTAP, ELAVL1, and CDH2 in ovarian cancer was analyzed using CPTAC datasets." (PMID 37684273, 2023). "Subsequently, we used the ssGSEA algorithm and overall survival analyses to identify the key prognosis-related immunological signatures in ovarian cancer, which included WTAP, ELAVL1, CDH2, and ALKBH5." (PMID 37684273, 2023). "ALKBH5 suppressed autophagy and enhanced proliferation and invasion via BCL-2 and miR-7 in epithelial ovarian cancer." (PMID 36545327, 2022). "In ovarian cancer, downregulated FTO and ALKBH5 induced FZD10 upregulation, which led to reducing PARPi sensitivity." (PMID 34745970, 2021). "Increased ALKBH5 further targeted the NANOG transcript by increasing m6A level, therefore contributing to increased ovarian cancer stem cell generation and carcinogenesis." (PMID 33814008, 2021). "Normal ovarian cell line (IOSE), ovarian cancer cell lines (A2780, SKOV‐3, HO8910 and OVCAR3) and endometrial cancer cell line (Ishikawa) were used to analyse the expression levels of ALKBH5 mRNA." (PMID 32329191, 2020). "To prove that ALKBH5 affects the methylation of NANOG, we performed m6A‐Seq to map the m6A modification in co‐cultured ovarian cancer cells." (PMID 32329191, 2020). "Furthermore, we investigated the prognostic role of ALKBH5 and IGF2BP2 in ovarian cancer, which both showed the overexpression of ALKBH5 and IGF2BP2 represented the worse prognosis for ovarian cancer." (PMID 38637813, 2024). "However, few studies have focused on the role of ALKBH5 and IGF2BP2 in regulating macrophage polarization in ovarian cancer." (PMID 38637813, 2024). "To further prove the relationship between ALKBH5 and M2 macrophage markers in TME of ovarian cancer, we found that ALKBH5 positively correlated with M2 macrophage markers IL-10 and CD163 through Pearson analysis in ovarian cancer related dataset GSE158739." (PMID 38637813, 2024). "Furthermore, we tried to investigate the role of ALKBH5 and IGF2BP2 played in macrophages in ovarian cancer." (PMID 38637813, 2024). "In order to investigate whether ALKBH5 and IGF2BP2 regulated the immune status of ovarian cancer by influencing the polarization of macrophages, we investigated that the correlation between ALKBH5 and IGF2BP2 with M2 macrophage polarization-related genes." (PMID 38637813, 2024). "In ovarian cancer, high expression of TLR4 could activate NF-κB signaling pathway, thus up-regulated ALKBH5 to influence the m6A methylation of NANOG, which further promoted carcinogenesis in ovarian cancer." (PMID 38637813, 2024).